MFSD2A (MFSD2 lysolipid transporter A, lysophospholipid)
Description:
Sodium-dependent lysophosphatidylcholine (LPC) symporter, which plays an essential role for blood-brain barrier formation and function. Specifically expressed in endothelium of the blood-brain barrier of micro-vessels and transports LPC into the brain (By similarity). Transport of LPC is essential because it constitutes the major mechanism by which docosahexaenoic acid (DHA), an omega-3 fatty acid that is essential for normal brain growth and cognitive function, enters the brain. Transports LPC carrying long-chain fatty acids such LPC oleate and LPC palmitate with a minimum acyl chain length of 14 carbons (By similarity). Does not transport docosahexaenoic acid in unesterified fatty acid (By similarity). Specifically required for blood-brain barrier formation and function, probably by mediating lipid transport (By similarity). Not required for central nervous system vascular morphogenesis (By similarity). Acts as a transporter for tunicamycin, an inhibitor of asparagine-linked glycosylation. In placenta, acts as a receptor for ERVFRD-1/syncytin-2 and is required for trophoblast fusion.
Synonyms: NLS1; HsMFSD2A; MFSD2; FLJ14490; SLC59A1; MCPH15; NEDMISBA
Tractability: Antibody: UniProt places it where antibodies can reach, with high confidence; its Gene Ontology location is reachable by antibodies, with high confidence; UniProt predicts a signal peptide or a membrane-spanning region.
Gene: Protein-coding gene on chromosome 1 (39,955,112 to 39,969,968, forward strand). Ensembl gene ENSG00000168389.
Subcellular location: Cell membrane; Endoplasmic reticulum membrane
Subcellular location (Human Protein Atlas): Cytosol; Plasma membrane; Cytoplasmic bodies
Pathways (Reactome):
Metabolism: Synthesis of PC
Gene Ontology:
Molecular function: long-chain fatty acid transmembrane transporter activity; lysophospholipid:sodium symporter activity; oleate transmembrane transporter activity; fatty acid transmembrane transporter activity; phospholipid transfer activity; lysophosphatidylcholine flippase activity; symporter activity
Biological process: brain development; cognition; fatty acid transport; lipid transport across blood-brain barrier; lysophospholipid translocation; lysophospholipid transport; regulation of phosphatidylcholine metabolic process; cellular response to starvation; embryonic brain development; energy homeostasis; establishment of blood-brain barrier; establishment of blood-retinal barrier; hippocampus development; long-chain fatty acid transport; maintenance of blood-brain barrier; motor behavior; negative regulation of fatty acid beta-oxidation; phosphatidylcholine biosynthetic process; photoreceptor cell morphogenesis; photoreceptor cell outer segment organization; positive regulation of cell growth; positive regulation of triglyceride biosynthetic process; regulation of dendrite development; regulation of multicellular organism growth; regulation of neuron projection arborization; and 9 more
Cellular component: lysosome; plasma membrane; endoplasmic reticulum membrane; membrane
Genetic constraint (gnomAD): Loss-of-function variants: 27 observed, 65.09 expected, observed/expected ratio (o/e) 0.41, 90% interval 0.31 to 0.57. The upper end of that interval is the gene's LOEUF score, 0.57, which puts it in group 2 of 6, group 1 being the genes least tolerant of losing a copy. Missense variants: 472 observed, 694.36 expected, observed/expected ratio (o/e) 0.68, 90% interval 0.63 to 0.73. Synonymous variants: 258 observed, 280.8 expected, observed/expected ratio (o/e) 0.92, 90% interval 0.83 to 1.02.
Homologues: Orthologues: chimpanzee MFSD2A (99% identical), macaque MFSD2A (97% identical), pig MFSD2A (89% identical), dog MFSD2A (89% identical), rat Mfsd2a (87% identical), mouse Mfsd2a (85% identical), guinea pig MFSD2A (85% identical), rabbit MFSD2A (81% identical), tropical clawed frog mfsd2a (67% identical), zebrafish mfsd2ab (63% identical), zebrafish mfsd2aa (60% identical), Caenorhabditis elegans mfsd-12 (17% identical). Paralogues in human: MFSD2B (39% identical), MFSD12 (18% identical).
Diseases named in the same sentence as MFSD2A in open-access papers:
MFSD2A is named in the same sentence as 79 diseases in open-access papers, as found by Europe PMC text mining. Sharing a sentence is not in itself a finding about the gene and the disease. The quoted sentences say what the papers report.
microcephaly (18 papers, 2017 to 2025). A congenital or acquired developmental disorder in which the circumference of the head is smaller than normal for the person's age and sex. "Mice deficient in MFSD2a have severe microcephaly, brain DHA deficiency, and learning and memory deficits." (PMID 38068814, 2023). "The physiological importance of Mfsd2a in brain development and function is underscored by the observation that Mfsd2a knockout mice (2aKO) display severe microcephaly, hypomyelination deficiency in brain DHA, and deficits in learning and memory." (PMID 37467896, 2023). "Patients with Mfsd2a-inactivating mutations exhibit severe hypomyelination in addition to microcephaly." (PMID 37104036, 2023). "Mice with gene-targeted deletion of Mfsd2a (2aKO mice) exhibited severe microcephaly and brain DHA deficiency." (PMID 37104036, 2023). "One of the prominent brain phenotypes of Mfs2a deficiency induced at either the BBB or conventionally in the entire mouse is microcephaly and hypomyelination, similar to that in humans with loss-of-function mutations in Mfsd2a." (PMID 37104036, 2023). "Depending on the transporter residual activity, mutations in MFSD2A (MCPH15) gene is associated with either a progressive microcephaly syndrome or a much lethal phenotype." (PMID 35111754, 2021). "Two case studies have reported that inactivating mutations in the Mfsd2a (full or partial loss of function) cause human microcephaly and established a correlation between the degree of mutation and the severity of the pathology." (PMID 33930014, 2021). "Humans with homozygous inactivating mutations in the MFSD2a gene present severe microcephaly and intellectual impairments." (PMID 32117064, 2020). "Humans with homozygous mutations that inactivate the MFSD2a gene present intellectual disability and severe microcephaly." (PMID 31861865, 2019). "Similar to other genetic causes of postnatal microcephaly, such as Angelman Syndrome, Rett Syndrome, and Christianson Syndrome, postnatal neurons of Mfsd2a deficiency mouse models fail to fully arborize, a process that relies on lipogenesis." (PMID 30074985, 2018). "Mice with gene-targeted deletion of Mfsd2a (2aKO) exhibited severe microcephaly and brain DHA deficiency." (PMID 30074985, 2018). "Using an inducible endothelial-specific Mfsd2a deletion mouse model, we have definitively proven that Mfsd2a deficiency results in a unique form of microcephaly manifesting as postnatal microcephaly." (PMID 30074985, 2018). "Furthermore, MFSD2A gene mutations in humans have been associated with microcephaly, a disease that alters brain size and can result in seizures." (PMID 39596674, 2024). "Importantly, humans with loss-of-function mutations in MFSD2A (also known as microcephaly 15 autosomal recessive) presented with severe microcephaly and hypomyelination, indicating that LPC transport is critical for brain growth and myelination." (PMID 37104036, 2023). "Defects in Mfsd2a are linked to ailments from behavioral and motor dysfunctions to microcephaly." (PMID 37156797, 2023). "Interestingly, ZIKV was recently reported to disrupt Mfsd2a both in human brain endothelial cell cultures and neonatal mouse brain, causing fetal growth restriction and microcephaly in the latter." (PMID 33930014, 2021). "Moreover, humans with homozygous inactivating mutations in the MFSD2a gene present severe microcephaly and intellectual impairments." (PMID 32117064, 2020). "Importantly, similar to our findings in mice, humans with loss-of-function mutations in Mfsd2a are born with head circumferences in the normal or slightly reduced range, and develop severe microcephaly within the first year of life." (PMID 30074985, 2018). "Importantly, we have also identified 3 families with homozygous nonsynonymous loss-of-function mutations in Mfsd2a that presented with severe microcephaly and intellectual disability." (PMID 30074985, 2018).
microcephaly (continued). "Therefore, further studies are required to clarify the molecular mechanisms underlying the behavioral abnormalities and microcephaly in Mfsd2a KO mice." (PMID 28833063, 2017). "Moreover, individuals with loss-of-function mutations in MFSD2A (a.k.a Microcephaly 15 Autosomal Recessive) present with severe microcephaly and hypomyelination, indicating that LPC transport via Mfsd2a is essential for normal human brain development and myelination." (PMID 37467896, 2023). "2aOKO mice had normal brain weights at P8, which differed from the severe microcephaly exhibited by mice with conventional or endothelium-specific knockout of Mfsd2a." (PMID 37104036, 2023). "Mfsd2a-knockout mice have shown a marked decrease of docosahexaenoic acid (DHA) level in brain, exhibiting neuron loss, microcephaly and cognitive deficits, as DHA acts essentially in brain growth and integrity." (PMID 34566571, 2021). "Endothelial-specific deletion of Mfsd2a in mice leads to a microcephaly phenotype accompanied by a reduction in neuronal arborization and dendritic length." (PMID 35111754, 2021). "MFSD2a knock-out mice show reduced levels of DHA in brain accompanied by neuronal cell loss in hippocampus and cerebellum, and exhibit severe microcephaly, as well as deficits in both learning and memory." (PMID 32117064, 2020). "This reduction in brain size in 2aECKO mice was similar to the microcephaly of 2aKO mice and indicates that Mfsd2a in the BBB is essential for brain development." (PMID 30074985, 2018). "Additional support for an important role for MFSD2a in normal brain growth and development include studies of human non-lethal inactivating mutations in MFSD2a, which result in microcephaly, due to reduced white matter volume, and intellectual disability." (PMID 38068814, 2023). "Global Mfsd2a-KO mice are small and have severe microcephaly." (PMID 37463052, 2023). "Mfsd2a-knockout mice showed obviously decreased levels of DHA in brain, exhibiting the loss of hippocampal and cerebellar neurons, severe anxiety, cognitive deficits, as well as microcephaly." (PMID 34566571, 2021). "Furthermore, MFSD2a knock-out mice showed reduced levels of DHA in brain, deficits in learning and memory, neuronal cell loss in hippocampus and cerebellum, and severe microcephaly." (PMID 31861865, 2019). "Here, we demonstrate, using vascular endothelial-specific and inducible vascular endothelial-specific deletion of Mfsd2a in mice, that Mfsd2a is uniquely required postnatally at the BBB for normal brain growth and DHA accretion, with DHA deficiency preceding the onset of microcephaly." (PMID 30074985, 2018). "In addition to BBB defects, Mfsd2a knockout mice also exhibit microcephaly." (PMID 31429822, 2019). "Moreover, mice with a homozygous mutation of the sodium-binding residue Aspartate-96 to Alanine-96 in Mfsd2a, a mutation that completely inactivates lipid transport function but does not affect expression, also presented with microcephaly and DHA deficiency." (PMID 30074985, 2018). "In the current study, we provide genetic and biochemical evidence that Mfsd2a is required at the BBB during postnatal life to mediate normal brain growth and that DHA deficiency precedes the onset of microcephaly." (PMID 30074985, 2018).
cognitive deficits (11 papers, 2015 to 2025). "Brain DHA content has been shown to decrease significantly in Mfsd2a-deficient (Mfsd2a-knockout) mice and its deficiency could lead to cognitive deficits and severe anxiety." (PMID 26176541, 2015). "Besides, downregulation of major facilitator superfamily domain-containing protein 2a (Mfsd2a) might cause cognitive impairment in CCH rats by promoting transcytosis in endothelial cells and exacerbating BBB breakdown." (PMID 35783093, 2022). "LPC-bound DHA transport across the BBB is facilitated by MFSD2a; reduced LPC levels can impair this process, leading to lower DHA levels in the brain, neuronal cell loss, and cognitive deficits." (PMID 40390837, 2025). "Mfsd2a-deficient mice exhibit significantly lower brain DHA levels, resulting in neuronal loss and cognitive impairment due to DHA’s crucial role in brain development and maintenance." (PMID 39834810, 2024). "We found that after the 2VO procedure, the rats exhibited cognitive impairment, showed increased BBB leakage within the hippocampus, and had reduced expression of the Mfsd2a protein." (PMID 32612494, 2020). "In conclusion, Mfsd2a attenuated BBB damage and ameliorated cognitive impairment in CCH rats, and its protective effect on the BBB was achieved via inhibition of vesicular transcytosis." (PMID 32612494, 2020). "We also investigated the effects and mechanisms of Mfsd2a modulation on BBB damage and cognitive impairment in the CCH rats." (PMID 32612494, 2020). "The recombinant AAV (overexpressing Mfsd2a) upregulated the expression of Mfsd2a protein in the hippocampus of CCH rats, inhibited the active vesicle transcytosis, and ameliorated cognitive impairment of CCH rats." (PMID 32612494, 2020). "In the present experiment, the effect of Mfsd2a gene deletion (such as a gene knockout model) on CCH-induced cognitive impairment was not evaluated, and the relevant mechanisms were not further explored." (PMID 32612494, 2020). "At present, there is a lack of research on the effects of Mfsd2a in BBB damage and cognitive impairment after CCH." (PMID 32612494, 2020).
Alzheimer disease (5 papers, 2018 to 2023). A progressive, neurodegenerative disease characterized by loss of function and death of nerve cells in several areas of the brain leading to loss of cognitive function such as memory and language. "This is the first study that has analyzed MFSD2a protein level in the human blood under different stages of Alzheimer’s Disease." (PMID 31861865, 2019).
lung carcinoma (5 papers, 2011 to 2022). "Further studies in Asian lung cancer patients are needed to test the association of rs12072037 genotypes with MFSD2A mRNA levels in normal lung tissue and to clarify the role of this polymorphism in lung cancer progression and prognosis." (PMID 21736709, 2011). "Exogenous expression of MFSD2A in lung cancer cells can induce G1 phase block in vitro, which disrupts cancer cell adhesion and migration, and thus is a novel lung antioncogene." (PMID 35410462, 2022). "The MFSD2A gene maps within a linkage disequilibrium block containing the MYCL1-EcoRI polymorphism associated with prognosis and survival in lung cancer patients." (PMID 21736709, 2011). "SNP rs12072037 modulates MFSD2A promoter activity and thus might affect MFSD2A levels in normal lung and in lung tumors, representing a candidate ethnically specific genetic factor underlying the association between the MYCL1 locus and lung cancer patients' survival." (PMID 21736709, 2011). "Our data showed a significant decrease of Mfsd2a protein expression in vascular endothelial cells within brain metastases originating from primary breast cancer, lung cancer, and NEPC patient samples, as revealed by double immunofluorescence labeling with anti-Mfsd2a and anti-CD34 antibodies." (PMID 29844613, 2018).
breast carcinoma (4 papers, 2018 to 2023). "Disruption of BBB during breast cancer BM can be additionally promoted by the loss of a major facilitator superfamily domain 2a (Mfsd2a) expression in tumor endothelium." (PMID 37190188, 2023). "Consistent with that, one recent study reported a significant loss of PUFA especially omega 3 in breast cancer brain metastasis, by downregulation of its specific receptor, Major Facilitator Superfamily Domain Containing 2a (MFSD2a) on tumor endothelium." (PMID 31620124, 2019). "The known fusogenic proteins syncytin-1 and syncytin-2, together with the corresponding receptors ASCT2 and MFSD2A for syncytiotrophoblast fusion, are also linked to tumorigenic processes, whereby downregulation of syncytin-1 inhibits cell fusion between breast cancer cells and endothelial cells." (PMID 30781614, 2019). "Permeability of BBB can also be promoted due to the diminished expression of Mfsd2a that transport the essential fatty acids, such as DHA in breast cancer BM." (PMID 37190188, 2023). "To test whether levels of DHA were affected as a result of Mfsd2a down-regulation in the tumor endothelium, we also performed ‘lipidomic’ analyses using tumor tissue dissected from PDX models of breast cancer brain metastasis or matched tissue dissected from the non-injected brain hemisphere." (PMID 29844613, 2018).
Cerebral ischemia (4 papers, 2022 to 2025). Restriction of arterial blood supply to the brain associated with insufficient oxygenation to support the metabolic requirements of the tissue. "The primary and most direct consequence of Mfsd2a downregulation following cerebral ischemia is the disinhibition of caveolae‐mediated transcytosis." (PMID 41358569, 2025). "Recent studies have revealed that storax-induced attenuation of BBB impairment, which helps to halt the progression of cerebral ischemia, occurs through the upregulation of Mfsd2a and concurrent inhibition of Cav-1 in the endothelial cells." (PMID 39273347, 2024). "Recent research confirmed that storax attenuated BBB disruption by upregulating Mfsd2a and inhibiting Cav-1 in the endothelial cells in order to arrest the progression of cerebral ischemia." (PMID 37762391, 2023). "In our research, we confirmed that storax attenuated BBB disruption by upregulating Mfsd2a and inhibiting Cav-1 in the ECs, to arrest the progression of cerebral ischemia." (PMID 35873558, 2022).
Intellectual disability (4 papers, 2020 to 2023). "In this regard, homozygous mutation affecting a highly conserved MFSD2a residue associated with a progressive microcephaly syndrome is characterized by intellectual disability, spasticity, and absent speech." (PMID 32117064, 2020).
subarachnoid hemorrhage (4 papers, 2023 to 2025). A serious neurological disorder characterized by intracranial hemorrhage into the subarachnoid space. "Certain CNS disorders, such as subarachnoid hemorrhage, have been linked to BBB disruption due to Mfsd2a deficiency." (PMID 36820986, 2023). "Upregulation of Mfsd2a reverses BBB damage in subarachnoid hemorrhage rats, and such protection may attribute to the increased influx of omega‐3 fatty acids by Mfsd2a and inhibited caveolae‐based transcellular transport." (PMID 39548663, 2024). "This core finding—that Mfsd2a activation suppresses transcytosis—was directly replicated in a subarachnoid hemorrhage (SAH) model, where AAV‐mediated Mfsd2a overexpression protected the BBB via the same mechanism." (PMID 41358569, 2025). "Moreover, selective enrichment of Mfsd2a in rats was shown to attenuate caveolar transcytosis, BBB permeability, and neuronal injury in the days following experimentally induced subarachnoid hemorrhage." (PMID 39724015, 2024).
brain injury (3 papers, 2021 to 2024). Acute and chronic (see also brain INJURIES, CHRONIC) injuries to the brain, including the cerebral hemispheres, CEREBELLUM, and brain STEM. "Major facilitator superfamily domain-containing 2a (Mfsd2a) has been demonstrated to be critical in limiting the increase in BBB vesicle transcytosis following brain injury." (PMID 35820896, 2022). "Altogether, alterations in the secretion of Ang-1 (from brain vascular mural cells) or Ang-2 (from brain endothelia) following brain injury could influence endothelial transcytosis by modulating the Mfsd2a/caveolin-1 pathway." (PMID 34702292, 2021).